KCNK17 (potassium two pore domain channel subfamily K member 17)
Description:
K(+) channel that conducts voltage-dependent outward rectifying currents upon membrane depolarization. Voltage sensing is coupled to K(+) electrochemical gradient in an 'ion flux gating' mode where outward but not inward ion flow opens the gate. Homo- and heterodimerizes to form functional channels with distinct regulatory and gating properties. Present in the cardiac conduction system where it may regulate action potential duration and beating frequency of cardiac myocytes. Permeable to other monovalent cations such as Rb(+) and Cs(+) (By similarity).
Synonyms: TALK-2; TALK2; TASK4; K2p17.1; TASK-4
Tractability: Small molecule: it belongs to a druggable protein family. Antibody: UniProt places it where antibodies can reach, with high confidence; its Gene Ontology location is reachable by antibodies, with high confidence; UniProt predicts a signal peptide or a membrane-spanning region. PROTAC: a small molecule that binds it is known.
Target class: Two-pore domain potassium channel; Voltage-gated ion channel; Ion channel; Potassium channels
Gene: Protein-coding gene on chromosome 6 (39,298,998 to 39,314,461, reverse strand). Ensembl gene ENSG00000124780.
Subcellular location: Cell membrane
Subcellular location (Human Protein Atlas): Cytosol; Plasma membrane; Nucleoplasm
Pathways (Reactome):
Muscle contraction: Phase 4 - resting membrane potential
Neuronal System: TWIK-related alkaline pH activated K+ channel (TALK)
Gene Ontology:
Molecular function: outward rectifier potassium channel activity; potassium channel activity; protein binding; protein heterodimerization activity; potassium ion leak channel activity
Biological process: potassium ion transport; potassium ion transmembrane transport
Cellular component: plasma membrane; membrane
Genetic constraint (gnomAD): Loss-of-function variants: 26 observed, 22.89 expected, observed/expected ratio (o/e) 1.14, 90% interval 0.83 to 1.57. The upper end of that interval is the gene's LOEUF score, 1.57, which puts it in group 6 of 6, group 1 being the genes least tolerant of losing a copy. Missense variants: 448 observed, 417.43 expected, observed/expected ratio (o/e) 1.07, 90% interval 0.99 to 1.16. Synonymous variants: 181 observed, 175.79 expected, observed/expected ratio (o/e) 1.03, 90% interval 0.91 to 1.16.
Homologues: Orthologues: chimpanzee KCNK17 (98% identical), rabbit KCNK17 (80% identical), pig KCNK17 (72% identical), macaque KCNK17 (69% identical), dog KCNK17 (63% identical), tropical clawed frog KCNK17 (42% identical), Drosophila melanogaster CG34396 (27% identical), Drosophila melanogaster Ork1 (25% identical), Caenorhabditis elegans twk-21 (25% identical), Caenorhabditis elegans twk-22 (23% identical), zebrafish kcnk12l (23% identical), Caenorhabditis elegans twk-26 (21% identical), and 12 more. Paralogues in human: KCNK16 (34% identical), KCNK5 (31% identical), KCNK4 (30% identical), KCNK10 (28% identical), KCNK2 (27% identical), KCNK6 (26% identical), KCNK15 (23% identical), KCNK3 (23% identical), KCNK1 (23% identical), KCNK9 (22% identical), KCNK12 (22% identical), KCNK13 (22% identical), and 2 more.
Diseases named in the same sentence as KCNK17 in open-access papers:
KCNK17 is named in the same sentence as 22 diseases in open-access papers, as found by Europe PMC text mining. Sharing a sentence is not in itself a finding about the gene and the disease. The quoted sentences say what the papers report.
migraine (3 papers, 2023). "Thirdly, the rare intergenic rs72854118-G near KCNK5 and KCNK17 is another variant providing insight into the pathogenesis of migraine." (PMID 37884687, 2023).
cardiac arrhythmia (2 papers, 2014 to 2021). Any disturbances of the normal rhythmic beating of the heart or MYOCARDIAL CONTRACTION. "A gain-of-function mutation (p.Gly88Arg) in the first pore domain of TALK-2, coded by KCNK17, causes a severe cardiac arrhythmia and is the only previously identified disease-associated mutation in TALK channels." (PMID 34032641, 2021). "Thus, the KCNK17 mutation is the first dominant-active arrhythmia-associated potassium channel mutation." (PMID 24972929, 2014). "Moreover, WES supports a second hit-hypothesis in severe arrhythmia cases and identified KCNK17 as a novel arrhythmia gene." (PMID 24972929, 2014).
heart failure (2 papers, 2021 to 2025). Inability of the heart to pump blood at an adequate rate to meet tissue metabolic requirements. "Reports of reduced KCNK17 mRNA levels in atrial fibrillation and heart failure suggest a role for K2P17.1 (TALK-2) in the pathophysiology of important cardiac pathologies." (PMID 34831137, 2021).
liver cancer (2 papers, 2019 to 2021). An epithelial or non-epithelial malignant neoplasm that arises from the liver. "We observed reduced expression of KCNK2, KCNK15, and KCNK17 in liver cancer, as well as overexpression of KCNK9, all of which correlated with a better prognosis for HCC patients per survival analyses." (PMID 31581133, 2019).
cardiac conduction disorder (1 paper, 2014). "In the present study, WES was utilized to identify the KCNK17 gene encoding the K2P channel TASK-4 as a novel disease gene that might be functionally relevant for cardiac conduction disorders." (PMID 24972929, 2014).
cardiomyopathy (1 paper, 2025). A disease of the heart muscle or myocardium proper. "The KCNK17-rs2815063-A allele was associated with a reduced LVEF in patients diagnosed with a cardiomyopathy grade ≥3 after adjusting for cardiac medication (p = 7.5 × 10−6)." (PMID 40413218, 2025). "After classification into therapy-based risk groups, the association between KCNK17-rs2815063-A and LVEF reduction was stronger in the high and moderate cardiomyopathy risk groups (p = 9.6 × 10−4 and p = 1.4 × 10−4, respectively), compared to the low-risk group (p = 0.002)." (PMID 40413218, 2025).
ischemic stroke (1 paper, 2021). A stroke disorder caused by obstruction of blood flow to the brain, due to thrombotic (local blood clot formation) or embolic (due to a blood clot or other material traveling from another site) event. "Single nucleotide polymorphisms in the KCNK17 gene which increase K2P17.1 (TALK-2) channel subunit expression levels are associated with the occurrence of ischemic stroke in Caucasians but not in a Chinese population." (PMID 34831137, 2021).
type 2 diabetes (1 paper, 2026). "Therefore, polymorphisms in KCNK17 that increase TALK-2 activity or expression would be predicted to increase type 2 diabetes risk by blunting beta cell glucose-stimulated Ca2+ influx, limiting GSIS, promoting Ca2+ER leak and elevating basal insulin secretion." (PMID 41739147, 2026).
Ventricular arrhythmia (1 paper, 2019). "While KCNK17 channels expressed in human heart atrial tissue represent potential therapeutic targets to treat atrial and ventricular arrhythmias, to the best of our knowledge, our study is the first to report dysregulated expression of KCNK15 and KCNK17 mRNA and protein in HCC tissues." (PMID 31581133, 2019).
cancer (1 paper, 2019). A tumor composed of atypical neoplastic, often pleomorphic cells that invade other tissues. "The data show that mRNA expression of KCNK1, KCNK7, and KCNK9 is upregulated in cancer tissues while KCNK2, KCNK3, KCNK5, KCNK10, KCNK13, KCNK15, and KCNK17 levels are decreased compared to controls." (PMID 31581133, 2019).
tumor (1 paper, 2019). "On the other hand, mRNA levels of KCNK3, KCNK13, KCNK15, and KCNK17 correlated positively with tumor differentiation." (PMID 31581133, 2019). "Next, we used Western Blot to measure the protein levels of KCNK2, KCNK9, KCNK15, and KCNK17 in four pairs of HCC tissues and matched non-tumor tissues." (PMID 31581133, 2019). "To confirm our conclusions above, we used qRT-PCR to measure the mRNA levels of KCNK2, KCNK9, KCNK15, and KCNK17 in 90 pairs of HCC specimens and matched non-tumor specimens, which were surgically removed from HCC patients." (PMID 31581133, 2019).
KCNK17 also shares sentences with these, for which no sentence is quoted: Arrhythmia (1 paper); atrial fibrillation (1); atrioventricular block (1); conduction disorder (1); diabetes (1); epilepsy (1); Headache (1); hepatocellular carcinoma (1); idiopathic ventricular fibrillation (1); papillary thyroid carcinoma (1); thyroid cancer (1).